FGF21 (fibroblast growth factor 21)
Diseases named in the same sentence as FGF21 in open-access papers (continued):
Sharing a sentence is not in itself a finding about the gene and the disease.
Hypertension (continued). "On the basis of above results, it is attractive to investigate the role of FGF21 on hypertension by gene knockdown or knockout of FGF21 receptors (klb-FGFRs) in the NTS and NG in further investigation." (PMID 27387420, 2016). "But there are only limited information about the relationships of FGF21 and hypertension in literature." (PMID 25850006, 2015). "A cross-sectional study conducted in US adults showed that serum FGF21 level, independent of age, BMI, eGFR and blood glucose, was associated with hypertension." (PMID 40356318, 2025). "However, there are discrepancies between Western and Eastern populations in circulating FGF21 and the prevalence of hypertension." (PMID 40356318, 2025). "FGF21 is also a promising therapeutic target for hypertension." (PMID 40356318, 2025). "FGF21 is a potential biomarker for the assessment of hypertension." (PMID 40356318, 2025). "Therefore, in this study, we aimed to explore the relationship of FGF21 with BP and hypertension in a Chinese population." (PMID 40356318, 2025). "Given the hypertension and circulating FGF21 differences between Western and Eastern populations, it is logical to deduce that the relationship between circulating FGF21 and hypertension in Asian population could be different from Western population." (PMID 40356318, 2025). "Our findings suggested that FGF21 could be a biomarker that can be measured in the onset and development of hypertension according to our up-to-date data on a Chinese population." (PMID 40356318, 2025). "Moreover, FGF21 levels predict the prognosis of many heart diseases such as hypertension, dilated cardiomyopathy, and MI." (PMID 37416922, 2023). "FGF21 ameliorates hypertension and target organ damage through different signaling pathways." (PMID 37576954, 2023). "Similarly, there were increased serum levels of FGF21 in elderly patients with hypertension and carotid atherosclerosis, and FGF21 levels can be used to diagnose carotid atherosclerosis and predict prognosis." (PMID 37576954, 2023). "In addition, Refined-JinQi-JiangTang tablets reduce hypertension by activating the FGF21/FGFR1 signaling pathway." (PMID 37576954, 2023). "Additionally, FGF21 derived from brown adipose tissue was found to attenuate adverse cardiac remodeling in mice with hypertension." (PMID 37416922, 2023). "At the population level, FGF21 has been independently associated with hypertension, although a distinction between sex has not been reported." (PMID 33996935, 2021). "Moreover, FGF21 levels correlated with both the clinical (adiposity, arterial hypertension) and biochemical (TGs, HDL-C) features of MS." (PMID 32546231, 2020). "Furthermore, A2aAR-induced thermogenesis in brown adipose tissue was important for secretion of fibroblast growth factor 21 (FGF21), which was necessary to protect against hypertension-induced cardiac remodeling." (PMID 33050467, 2020). "FGF21 concentration was markedly elevated in the subjects with arterial hypertension and high TGs levels compared with the concentrations in children with normal blood pressure [124.6 pg/ml vs 75.2 pg/ml, p = 0.0004] and normal TGs levels [124.6 pg/ml vs 81.1 pg/ml, p = 0.0035]." (PMID 32546231, 2020). "This suggests a protective role for FGF21 against hypertension." (PMID 32858953, 2020). "FGF21 ameliorated the hypertension and BRS impairment in HFD, which may be mediated by its receptors located in baroreflex afferent pathway." (PMID 27387420, 2016). "However, the direct targets and mechanisms linking FGF21 to blood pressure control and hypertension are still elusive." (PMID 27387420, 2016). "In female patients, logistic regression analysis of LEAD showed that age (OR, 1.235; 95%CI (1.133-1.347); P < 0.001), hypertension (OR, 3.231; 95%CI 1.102-9.470; P = 0.033), FGF21 (OR, 1.106; 95%CI 1.008-1.223; P = 0.028) were independent impact factors for LEAD." (PMID 25850006, 2015). "However, circulating level of FGF21 is markedly elevated in those with hypertension." (PMID 40356318, 2025).
Hypertension (continued). "Besides its use as a biomarker, FGF21 may be a new drug target for hypertension treatment." (PMID 40356318, 2025). "FGF-21 also alleviates renal inflammatory infiltration and lipotoxicity, but FGF-21-induced hypertension is noteworthy." (PMID 40725208, 2025). "The aim of this study is to explore the relationship between FGF21 levels and vascular diseases (VDs) including carotid atherosclerosis (CAS) and hypertension (HP) in patients with T2DM." (PMID 38057786, 2023). "Serum FGF21 levels were significantly elevated in patients with AMI, coronary artery disease, hypertension, and dilated cardiomyopathy." (PMID 36778154, 2023). "Patients in the non-survivor group were older, had lower diastolic blood pressure, total cholesterol, phosphate and higher FGF21, TACS, ATACS, AoACS, DTACS, and were more likely to have hypertension compared to those in the survivor group (p < 0.05)." (PMID 37724523, 2023). "This study aimed to investigate the relationship between serum FGF21 and vWF expression and carotid atherosclerosis (CAS) in elderly patients with hypertension." (PMID 35242298, 2022). "Among 14 studies, 9 studies reported that serum FGF21 concentration was significantly higher in patients with CVDs, including CAD and hypertension." (PMID 34513950, 2021). "Overall, the serum FGF21 concentration was significantly higher in CVD patients (p < 0.001), especially for coronary artery disease (CAD) (p < 0.001) and hypertension (p < 0.001)." (PMID 34513950, 2021). "Second, relevant comorbidities including DM, hypertension and CHD in CKD patients affected plasma FGF21 concentration." (PMID 21525989, 2011). "More recent studies indicate that BAT is a source of FGF21 and that FGF21 derived specifically from BAT exerts a protective effect on the heart by acting as a preventative against deleterious cardiac remodeling in response to hypertension in mice." (PMID 40149686, 2025). "The relationship between serum FGF21 and vWF expression and CAS in elderly patients with hypertension remains unclear." (PMID 35242298, 2022). "Previous studies suggested that Fgf21 also act as a negative-feedback protective factor that can provide a protective effect in some pathological conditions, including hypertension and alcoholic cardiomyopathy." (PMID 34708083, 2021). "As antihypertensive treatments decrease the level of circulating FGF21, this treatment group was excluded from analysis to better understand the role of FGF21 in hypertension irrespective of antihypertensive treatment." (PMID 32858953, 2020). "The relationship between FGF21 and RAS was reported in former studies and the resulting hypertension may occur with similar mechanisms in PE; thus, in the present study we examined placental FGF21 expression, and more intense FGF21 expression was found in placentas with PE." (PMID 37374349, 2023). "Besides, this study did not investigate various targeted treatments for hypertension, so the effects of these treatments on FGF21 and vWF levels are unclear." (PMID 35242298, 2022). "Overall, the serum FGF21 concentration was significantly higher in CVD patients than in those without CVDs [standard mean difference (SMD) = 0.58, 95% CI: 0.33–0.84, p < 0.001], especially for CAD (SMD = 0.75, 95% CI: 0.42–1.09, p < 0.001) and hypertension (SMD = 0.48, 95% CI: 0.37–0.59, p < 0.001)." (PMID 34513950, 2021). "However, the direct downstream targets of FGF21 for the development of hypertension have not been revealed." (PMID 27387420, 2016). "Recently, numerous studies have focused on the association between FGF21 and cardiovascular disease, and circulating FGF21 levels have been demonstrated to be elevated in patients with certain chronic ailments such as carotid atherosclerosis, coronary artery disease (CAD), and hypertension." (PMID 26091256, 2015).
Hypertension (continued). "Fourth, we could not measure hepatokines such as fetuin-A, fibroblast growth factor 21, and selenoprotein P and levels of renin, angiotensin II and aldosterone which could explain the mechanism for an independent role of NAFLD in incident hypertension." (PMID 26618774, 2015). "Furthermore, all CKD subjects with other comorbidities including DM, hypertension and CHD in this study had significantly higher plasma FGF21 levels (1422±302.9 pg/ml, n = 9) than those without corresponding comorbidities (611.2±111.5 pg/ml, n = 55, p = 0.0091)." (PMID 21525989, 2011).
liver fibrosis (76 papers, 2012 to 2026). "By overexpressing FGF21 in mouse hepatocytes, they demonstrated that ferroptosis can be inhibited, thereby rescuing liver fibrosis caused by iron overload." (PMID 40406118, 2025). "It would be of interest to further define the in vivo mechanistic role of FGF21 in liver fibrosis associated with SIRT1 loss during aging." (PMID 36999514, 2023). "To further understand the underlying mechanisms by which FGF21 prevents liver fibrosis, we measured hepatic expression of key genes involved in fibrogenesis." (PMID 36648330, 2023). "These revealed that both NAFLD activity and liver fibrosis were associated with both CD36hi ResKCs, CD36hi MoKCs, and CD9hi MoKCs, indicating that FGF21 likely improves liver fibrosis by reducing these lipid- and scar-associated macrophages." (PMID 36648330, 2023). "For example, in obese diabetic mice fed a methionine and choline-deficient diet (MCD), an FGF21 analog significantly reduces fibrogenic expression and inhibits hepatic fibrosis." (PMID 33381084, 2020). "Moreover, mice with FGF21 deficiency showed more aggravated liver fibrosis and bile duct proliferation in BDL-induced cholestasis for the first time." (PMID 39040469, 2024). "Moreover, FGF21 decreased lipid- and scar-associated macrophages, which correlated with less hepatic fibrosis as demonstrated by reduced collagen accumulation." (PMID 36648330, 2023). "Therefore, we aimed to evaluate rs738409 patanin-like phospholipase domain-containing protein (PNPLA3) and rs499765 FGF21 polymorphisms in T2D, and their association with NAFLD, liver fibrosis, and serum biomarkers (FGF21 and cytokeratin 18 levels)." (PMID 35630668, 2022). "Similarly, in an alcohol-induced model of hepatic fibrosis, loss of FGF21 exacerbates liver injury and fibrosis." (PMID 33381084, 2020). "Since FGF21 has been used to treat liver fibrosis by alleviating metabolic dysfunction, a comparison of its effects with those of FGF18 on HSCs and hepatocytes is of interest." (PMID 40678531, 2025). "Efruxifermin, a long-acting Fc-FGF21 analog that directly inhibits hepatic stress and collagen deposition, has been clinically reported to significantly ameliorate hepatic fibrosis and steatosis." (PMID 40492139, 2025). "Liver collagen stained by Picrosirius red was higher in lipodystrophic mice than control mice at 22°C, and this hepatic fibrosis was reduced visually and quantitatively by FGF21 treatment." (PMID 40663389, 2025). "Several pharmacological agents including incretin-based strategies, FGF21 analogues and the panPPAR agonist lanifibranor target the interface of MASLD and T2DM and have thereby shown promise to improve MASH and associated liver fibrosis." (PMID 41362583, 2025). "Phase II clinical trials involving FGF21 agonists have demonstrated improvement of liver fibrosis and resolution of MASH." (PMID 40496439, 2025). "Some drug classes, such as FGF21 analogs, have shown potential to reverse fibrosis, with reduction in liver fibrosis biomarkers alongside improvements in liver fat and inflammation." (PMID 40004939, 2025). "A FGF-21 analogue (Pegozafermin) shows significant effects on liver fibrosis in biopsy-proven MASH patients in a clinical trial." (PMID 39411175, 2024). "First, FGF21 overexpression alleviates BDL-induced liver fibrosis and bile duct proliferation accompanied by gallbladder volume expansion." (PMID 39040469, 2024). "Phase 2 trials with liver-directed mechanisms (Efruxifermin, Pegozafermin) that target FGF-21 or weight-loss combinations of GLP-1/GIP/Glucagon (Tirzepatide, Survodutide) have shown improvement in liver fibrosis and are currently in phase 3 investigations." (PMID 39589962, 2024). "FGF21 overexpression protected against BDL-induced liver fibrosis, as proved by the decreasing α-SMA at both the mRNA and protein levels." (PMID 39040469, 2024).
liver fibrosis (continued). "The relationship between FGF21 and cardiorespiratory fitness is also of great interest given that VO2peak is associated with histologic NASH activity and liver fibrosis and also overall mortality in the general population as well as NAFLD." (PMID 36986211, 2023). "The transplantation of FGF21-ADMSC significantly improved liver fibrosis by decreasing serum hyaluronic acid and reducing fibrosis-related factors’ expression." (PMID 37108631, 2023). "The submerged mechanism is that FGF21 ameliorates PDGF-BB-induced HSCs fibrogenesis by blocking the PDGF-leptin-hepatic fibrosis axis." (PMID 35677107, 2022). "Studies evidenced that exogenous FGF21 can reduce the liver fibrosis degree in the metabolic model of mice." (PMID 36618930, 2022). "In conclusion, these data indicate differing roles for CCR2-CCL2 and FGF21 pathways in the pathogenesis of liver fibrosis and chronic steatohepatitis in human NAFLD, corroborating the potential distinct benefits of pharmacological targeting each pathway." (PMID 35743140, 2022). "Such excessive iron accumulation enhanced ferroptosis in hepatocytes by inducing heme oxygenase 1 (HO-1) expression, which contributed to the progression of liver fibrosis, accompanied by the upregulation of the FGF21 protein level in vitro and in vivo." (PMID 36703745, 2022). "Ample evidence shows that the use of exogenous FGF21 can reduce the degree of liver fibrosis in metabolic model mice." (PMID 35677107, 2022). "The latest studies on the effect of FGF21 on liver fibrosis in haemochromatosis and ferroptosis bring good news for GH patients." (PMID 35677107, 2022). "The beneficial effects of hepatokines include 1) improvement of insulin sensitivity (FGF21); 2) prevention of liver fibrosis (FGF21, HMGB1, PST, AHSG and SERPINF1) and 3) reduction of inflammation and lipid accumulation (FGF21, HMGB1 and LECT2)." (PMID 36267567, 2022). "Compared with other organs, the function of regulating bile acids, glucose, and lipid metabolism of FGF21 is of prime importance in improving liver fibrosis." (PMID 35677107, 2022). "The regulating function of glucose and lipid metabolism of FGF21 is of primary importance in improving liver fibrosis." (PMID 36618930, 2022). "Recombinant FGF21 significantly protected against liver fibrosis by inhibiting hepatocyte ferroptosis." (PMID 36703745, 2022). "FGF21 reduces the levels of inflammatory factors (IL-1β, IL-6, and TNF-α) significantly, achieving therapeutic effects on liver fibrosis, underling the TGF-β signaling pathway." (PMID 35677107, 2022). "Interventional studies report beneficial effects of B1344, a long-acting polyethylene glycosylated (PEGylated) FGF21 analogue, on lowering hepatic fibrosis and protecting against the progression of NASH in rodents and nonhuman primates." (PMID 35677107, 2022). "Compared with the 16 patients without severe liver fibrosis/cirrhosis, the 6 patients with severe liver fibrosis/cirrhosis had markedly elevated baseline FGF21 levels." (PMID 34521419, 2021). "Fibroblast growth factor‐21 (FGF21), which is expressed in fat, skeletal muscle, and liver, increases glucose‐induced ISF in rodent islets, and the plasma FGF21 increases with the severity of liver fibrosis in NAFLD." (PMID 33102766, 2020). "We conclude that FGF21 acts as an inhibitor of the succinate-GPR91 pathway to control liver fibrosis." (PMID 29444136, 2018). "In this study, we evaluated the role of LY2405319, an analogue of FGF21, in hepatic stellate cell (HSC) activation and in a methionine and choline-deficient (MCD)-diet induced mouse model of liver fibrosis." (PMID 29444136, 2018). "A few animal studies have also now been published identifying the mechanisms by which FGF15/19 and FGF21 mediate the development of hepatic fibrosis." (PMID 27699175, 2016).